SLC39A7 (solute carrier family 39 member 7)
Description:
Transports Zn(2+) from the endoplasmic reticulum (ER)/Golgi apparatus to the cytosol, playing an essential role in the regulation of cytosolic zinc levels. Acts as a gatekeeper of zinc release from intracellular stores, requiring post-translational activation by phosphorylation, resulting in activation of multiple downstream pathways leading to cell growth and proliferation. Has an essential role in B cell development and is required for proper B cell receptor signaling. Plays an important role in maintaining intestinal epithelial homeostasis and skin dermis development by regulating ER function (By similarity). Controls cell signaling pathways involved in glucose metabolism in skeletal muscle (By similarity). Has a protective role against ER stress in different biological contexts. Mediates Zn(2+)-induced ferroptosis.
Synonyms: ZIP7; HKE4; RING5; H2-KE4; D6S2244E; KE4; AGM9; D6S115E
Tractability: Small molecule: a structure with a bound ligand is known. Antibody: UniProt predicts a signal peptide or a membrane-spanning region. PROTAC: ubiquitination databases record sites on it; its protein half-life has been measured.
Target class: Transporter
Gene: Protein-coding gene on chromosome 6 (33,200,305 to 33,204,439, forward strand). Ensembl gene ENSG00000112473.
Subcellular location: Endoplasmic reticulum membrane; Golgi apparatus, cis-Golgi network membrane
Subcellular location (Human Protein Atlas): Endoplasmic reticulum; Nucleoplasm
Pathways (Reactome):
Transport of small molecules: Zinc influx into cells by the SLC39 gene family
Gene Ontology:
Molecular function: protein binding; zinc ion transmembrane transporter activity; metal ion transmembrane transporter activity
Biological process: B cell differentiation; intracellular zinc ion homeostasis; regulation of ferroptosis; zinc ion transmembrane transport; metal ion transport; skin epidermis development; transmembrane transport
Cellular component: endoplasmic reticulum; endoplasmic reticulum membrane; membrane; Golgi apparatus
Genetic constraint (gnomAD): Loss-of-function variants: 25 observed, 41.76 expected, observed/expected ratio (o/e) 0.6, 90% interval 0.44 to 0.84. The synonymous counts are far from expectation, so gnomAD's model fits this gene poorly and the ratio says little. Missense variants: 501 observed, 620.62 expected, observed/expected ratio (o/e) 0.81, 90% interval 0.75 to 0.87. Synonymous variants: 181 observed, 246.95 expected, observed/expected ratio (o/e) 0.73, 90% interval 0.65 to 0.83.
Gene-disease validity (ClinGen):
ClinGen rates the evidence that SLC39A7 causes each of these diseases.
agammaglobulinemia (autosomal recessive): Moderate. A decreased level of serum immunoglobulins.
Homologues: Orthologues: chimpanzee SLC39A7 (99% identical), macaque SLC39A7 (98% identical), dog SLC39A7 (92% identical), rabbit SLC39A7 (91% identical), guinea pig SLC39A7 (89% identical), mouse Slc39a7 (87% identical), rat Slc39a7 (86% identical), pig SLC39A7 (84% identical), tropical clawed frog slc39a7 (54% identical), zebrafish slc39a7 (50% identical), Drosophila melanogaster Catsup (48% identical), Caenorhabditis elegans zipt-7.2 (45% identical), and 1 more. Paralogues in human: SLC39A13 (27% identical).
Diseases named in the same sentence as SLC39A7 in open-access papers:
SLC39A7 is named in the same sentence as 61 diseases in open-access papers, as found by Europe PMC text mining. Sharing a sentence is not in itself a finding about the gene and the disease. The quoted sentences say what the papers report.
breast carcinoma (36 papers, 2008 to 2025). "Elevated expression of SLC39A7 was also reported in tamoxifen-resistant breast cancer cells." (PMID 36142814, 2022). "Our findings were consistent with those of the previous study, in that high mRNA expression levels of SLC39A6 and SLC39A14 indicated favorable OS, but upregulated SLC39A2-5, SLC39A7, and SLC39A12-13 were associated with poor OS in the patients with breast carcinoma." (PMID 34925450, 2021). "Moreover, SLC39A7 has been reported to play a significant role in several cancers, such as cervical cancer, gastric cancer, and breast cancer 14-16." (PMID 34149917, 2021). "Increased levels of zinc and SLC39A7 were found in tamoxifen-resistant breast cancer MCF-7 cells." (PMID 34149917, 2021). "Slc39a7/Zip7 was found to affect EGF/IGF signaling and tamoxifen resistancy of breast cancer cells." (PMID 18985159, 2008). "SLC39A7, also known as ZIP7, is activated by phosphorylation-mediated zinc release from intracellular stores, drives major pathways, such as MAPK, mTOR and PI3K-AKT, that are involved in cell survival and proliferation, and it was reported to be overactivated in breast cancer and cervical cancer." (PMID 34178683, 2021). "The role of necroptosis-related genes in breast cancer, such as FASLG, FLT3, HSPA4, IDH2, IPMK, LEF1, and SLC39A7, has not been extensively studied, and these necroptosis-related genes have been confirmed to regulate the biological processes of necroptosis in various types of tumors." (PMID 36675706, 2022).
colorectal cancer (8 papers, 2019 to 2025). A primary or metastatic malignant neoplasm that affects the colon or rectum. "Knockdown of SLC39A7 was show to inhibit cell growth and induce apoptosis in colorectal cancer (CRC)." (PMID 36142814, 2022). "Moreover, knockdown of SLC39A7 inhibited the growth of colorectal cancer cells through G2/M cell cycle arrest and apoptosis." (PMID 34149917, 2021). "In addition, the role of SLC39A7 in a variety of malignant tumors such as gastric cancer, cervical cancer, colorectal cancer, and prostate cancer has also been studied, but these studies on malignant tumors do not include liver cancer, but they also increase the credibility of our results." (PMID 35957801, 2022). "Furthermore, knockdown of SLC39A7 expression could result in the decrease in cell growth and the increase in cell apoptosis in colorectal cancer." (PMID 32109290, 2020).
cervical cancer (6 papers, 2017 to 2022). A primary or metastatic malignant neoplasm involving the cervix. "In this study, we investigated the effects of SLC39A7 in cervical cancer in vitro and elucidate related underlying mechanisms." (PMID 29285013, 2017). "We hypothesized that SLC39A7 might be implicated in the growth and aggressive behavior of cervical cancer cells." (PMID 29285013, 2017). "ZIP7 (SLC39A7) is a zinc transporter that was found to influence the progression of cervical cancer." (PMID 33287452, 2020). "Here, we demonstrated that knockdown of SLC39A7 leaded to decreased proliferation, migration and invasion, and induced apoptosis in cervical cancer cells." (PMID 29285013, 2017). "Using Oncomine data analysis, we first found SLC39A7 is commonly upregulated in cervical cancer tissues in comparison with corresponding normal controls." (PMID 29285013, 2017). "We supposed that the intracellular zinc pools were also decreased in SLC39A7-knockdown cervical cancer cells compared with control, resulting in downregulation of the Bcl-2/Bax ratio, hence allowing acceleration of apoptosis." (PMID 29285013, 2017). "In our experiments, the protein expression of MMP-2 was dramatically reduced in cervical cancer cells with SLC39A7 knockdown, probably as a result of overexpression of E-cadherin, thus promoted the invasion and metastasis of these cells." (PMID 29285013, 2017). "In the current study, we have characterized the tumor promoter activity of SLC39A7 in cervical cancer cells." (PMID 29285013, 2017). "Previous studies prompted us to explore the impact of SLC39A7 on the biological behavior of cervical cancers." (PMID 29285013, 2017). "The expression of SLC39A7 was found to be higher expressed in cervical cancer cell lines (HeLa, SiHa, CaSki, ME-180) than in normal cervical epithelial cell line H8 (p < 0.001)." (PMID 29285013, 2017). "Subsequently, we aimed to explore the function of SLC39A7 in cervical cancer in vitro." (PMID 29285013, 2017). "Our results firstly revealed that SLC39A7 may play a vital function in cervical cancer carcinogenesis by regulating apoptotic and epithelial to mesenchymal transition (EMT) progresses." (PMID 29285013, 2017). "We supposed that SLC39A7 may indirectly regulate MMP-2 by altering E-cadherin expression in cervical cancer." (PMID 29285013, 2017). "In the present study, stable knockdown of SLC39A7 increased the expression of E-cadherin, indicating the suppression of EMT of cervical cancer cells, leading to inhibition of invasiveness, proliferation and colony-formation." (PMID 29285013, 2017). "However, whether or not SLC39A7 is involved in human cervical cancer remains unclear." (PMID 29285013, 2017).
type 2 diabetes (6 papers, 2017 to 2021). "We also identified seven genes (Sardh, Slc39a7, Pfn1, Arg1, Cth, Sod1 and P4hb) in the liver and one gene (Fabp4) in the adipose tissue that may be associated with type 2 diabetes in gerbils." (PMID 29394254, 2018).
diabetes (5 papers, 2015 to 2023). "Slc39a7 was identified in our study, and significantly lower mRNA and protein levels in diabetic livers were observed, implying that Slc39a7 plays a key role in the mechanism of diabetes in gerbils." (PMID 29394254, 2018).
prostate carcinoma (5 papers, 2021 to 2024). A carcinoma that arises from epithelial cells of the prostate gland. "A recent report showed that METTL9-mediated methylhistidine modification on zinc transporter SLC39A7 regulates the growth of prostate cancers both in vitro and in vivo." (PMID 35402738, 2022). "SLC39A7 is critical for cell growth, invasion and migration of several malignances, including breast, cervical, gastric, colorectal and prostate cancers." (PMID 33535184, 2021). "By suppressing expression of SLC39A7 and activity of Wnt/β-catenin, miR-15a-3p inhibits cell proliferation and invasion in prostate cancer." (PMID 33535184, 2021).
glioma (4 papers, 2021 to 2022). A benign or malignant brain and spinal cord tumor that arises from glial cells (astrocytes, oligodendrocytes, ependymal cells). "Our results indicated that SLC39A7 is highly expressed in glioma and is associated with a poor prognosis." (PMID 34149917, 2021). "Through Kaplan-Meier analysis, SLC39A7 expression was found to be associated with decreased survival rates among all gliomas and different WHO grade gliomas in the CGGA database, and high SLC39A7 expression predicted poor survival rates among all glioma in the TCGA and Rembrandt databases." (PMID 34149917, 2021). "Recent data suggested SLC39A7 to promote glioma cell malignancy through the TNF-α-mediated NF-κB pathways." (PMID 36142814, 2022). "Taken together, these results indicated that the high expression of SLC39A7 mediated an oncogenic effect in glioma." (PMID 34149917, 2021). "To determine the specific signaling pathway of SLC39A7 involved in glioma, we performed GSEA based on the CGGA databases." (PMID 34149917, 2021). "To further confirm the mechanism of action of SLC39A7 in glioma, we conducted GSEA on the CGGA database." (PMID 34149917, 2021). "To investigate the expression and prognostic value of SLC39A7 in gliomas, we analyzed its expression in CGGA, TCGA and Rembrandt databases." (PMID 34149917, 2021). "Using bioinformatics analysis and in vivo and in vitro experiments, we found that SLC39A7 promotes glioma proliferation, invasion, migration and tumorigenesis via the TNFα-mediated NF-κB signaling pathway." (PMID 34149917, 2021). "Our results indicated that SLC39A7 significantly promoted the proliferation, invasion and migration of glioma cells." (PMID 34149917, 2021). "To further characterize the effect of SLC39A7 in glioma cells, we selected the U87 and LN229 cell lines for the overexpression of SLC39A7 since these cell lines had the lowest expression of SLC39A7 among all of the available cell lines." (PMID 34149917, 2021). "The invasion and migration of glioma cells were decreased following SLC39A7 knockdown, as determined by a transwell assay." (PMID 34149917, 2021). "SLC39A7 overexpression also increased the invasion and migration of these glioma cells compared with the control group." (PMID 34149917, 2021). "In orthotopic xenograft models, knockdown of SLC39A7 inhibited the glioma volume and increased nude mice's survival time." (PMID 34149917, 2021). "We determined that SLC39A7 promotes the malignant behaviors of glioma by activating the TNF-α-mediated NF-κB signaling pathway." (PMID 34149917, 2021). "A transwell assay showed that the increased invasion and migration of SLC39A7-overexpressing glioma cells were reversed by QNZ treatment." (PMID 34149917, 2021). "To characterize the relationship between SLC39A7 and IDH status, we found that SLC39A7 was highly enriched in IDH wild-type glioma in CGGA and TCGA databases." (PMID 34149917, 2021). "Rescue experiments involving QNZ treatment of SLC39A7-overexpressing glioma cells confirmed that the promotion effects of SLC39A7 were abrogated." (PMID 34149917, 2021). "Through analysis of the TCGA, CGGA and Rembrandt databases, we found that SLC39A7 was expressed more highly in GBM than in other grades of glioma." (PMID 34149917, 2021). "In three databases, we found that SLC39A7 was more highly expressed in WHO grade IV GBM than in WHO grade II or grade III glioma." (PMID 34149917, 2021). "SLC39A7 promotes malignant behaviors in glioma via the TNF-α-mediated NF-κB signaling pathway." (PMID 35945192, 2022). "In this study, we aimed to explore the role of SLC39A7 in glioma development." (PMID 34149917, 2021). "We further evaluated the effects of SLC39A7 on glioma tumorigenesis by orthotopic xenograft models." (PMID 34149917, 2021). "Then, we investigated the expression of SLC39A7 in our 70 glioma patients." (PMID 34149917, 2021). "This study revealed a novel gene, SLC39A7, that is highly expressed in glioma tissues and cells." (PMID 34149917, 2021).
glioma (continued). "SLC39A7 may, therefore, be a therapeutic target to inhibit glioma progression and improve the prognosis of patients." (PMID 34149917, 2021). "Patients and methods: Bioinformatic analysis was used to predict the role of SLC39A7 in glioma." (PMID 34149917, 2021). "In this study, we investigated the role and function of SLC39A7 in glioma." (PMID 34149917, 2021). "However, the function and mechanism of SLC39A7 in glioma remains unclear." (PMID 34149917, 2021). "All results, including qPCR, western blotting and IHC, showed that SLC39A7 was highly expressed, and expression was especially increased in higher WHO grade gliomas." (PMID 34149917, 2021). "IHC and clinical analysis showed that the expression of SLC39A7 was related to WHO grade and IDH status in 70 glioma patients." (PMID 34149917, 2021). "Furthermore, we detected the mRNA expression levels of SLC39A7 and TNF-α in 70 clinical glioma specimens." (PMID 34149917, 2021). "Moreover, both univariate and multivariate cox analyses showed that SLC39A7 expression, IDH status and WHO grades were independent prognostic factors of glioma patients." (PMID 34149917, 2021). "In summary, we found that the zinc transporter SLC39A7 is highly expressed in high-grade glioma patients with a poor prognosis and can activate the TNF-α-mediated NF-κB signaling pathway, thereby promoting the proliferation, invasion and migration of glioma cells." (PMID 34149917, 2021). "Therefore, SLC39A7 may activate the TNF-α-mediated NF-κB signaling pathway, thereby promoting the malignant progression of glioma." (PMID 34149917, 2021). "However, it is not clear whether SLC39A7 participates in the tumorigenesis and development of gliomas." (PMID 34149917, 2021).
gastric cancer (3 papers, 2020 to 2022). A primary or metastatic malignant neoplasm involving the stomach. "In gastric cancer, SLC39A7 induces gastric cancer cell proliferation and migration and inhibits apoptosis via the AKT/mTOR signaling pathway." (PMID 34149917, 2021). "Whereas, little is known about the role of SLC39A7 in gastric cancer (GC)." (PMID 32109290, 2020).
agammaglobulinemia (2 papers, 2019 to 2025). "More recently, Anzilotti et al39 identified compound heterozygous or homozygous rare variants in SLC39A7 (ZIP7) in patients with early onset agammaglobulinemia and the absence of B cells." (PMID 31402507, 2019).
lung adenocarcinoma (2 papers, 2023 to 2024). A carcinoma that arises from the lung and is characterized by the presence of malignant glandular epithelial cells. "SLC39A3, SLC39A4, and SLC39A7 expressions are linked to lung squamous cell carcinoma prognosis, with SLC39A7 playing a crucial role in lung adenocarcinoma (LUAD) cell survival and proliferation." (PMID 38534987, 2024). "The gene expression of SLC3A2, SLC16A1, SLC39A14, SLC39A7, SLC1A5, and SLC11A2 in the lung adenocarcinoma cell line A-549 and H1299 is higher than that in the normal lung epithelial cell line Beas-2B." (PMID 37973895, 2023). "The protein expression of SLC3A2, SLC11A2, SLC1A5, SLC16A1, SLC39A7, SLC39A14 in the lung adenocarcinoma cell line A-549 and H1299 is higher than that in the normal lung epithelial cell line Beas-2B." (PMID 37973895, 2023).
metabolic syndrome (2 papers, 2022). A cluster of metabolic risk factors for CARDIOVASCULAR DISEASES and TYPE 2 DIABETES MELLITUS. "We identified non-synonymous mutations e.g., in ApoM, Notch4, Slc39a7, Smim29 genes and other variations in or near genes associated with metabolic syndrome in human genome-wide association studies." (PMID 36014934, 2022).
neuroblastoma (2 papers, 2015 to 2017). Neuroblastoma (NB) is the most common solid, extracranial childhood tumor. "SLC39A6 is shown to mediate the incorporation of extracellular Zn2+ in SH-SY5Y neuroblastoma cells, however, whereas SLC39A7 regulates mobilization of Zn2+ from Golgi apparatus to the cytoplasm." (PMID 26010609, 2015).
asthma (1 paper, 2020). "A transcriptional profile study identified SLC39A7 as gene product associated with asthma." (PMID 32645059, 2020). "The solute carrier (SLC) protein SLC39A7, a Zn2+ importer, has recently been linked to asthma." (PMID 32645059, 2020).
gastric tumor (1 paper, 2020). "In gastric tumor model, it was reported that SLC39A7 expression was remarkably up-regulated, while the function and mechanism of SLC39A7 in GC is still not clear." (PMID 32109290, 2020).
lymph node metastasis (1 paper, 2020). "For patients with positive lymph node metastasis, SLC39A2, SLC39A3, SLC39A7, SLC39A8, SLC39A12 and SLC39A13 high expression suggested a worse OS, but SLC39A10 high expression suggested a benefit OS." (PMID 32744318, 2020).
osteoporosis (1 paper, 2025). A condition of reduced bone mass, with decreased cortical thickness and a decrease in the number and size of the trabeculae of cancellous bone (but normal chemical composition), resulting in increased fracture incidence. "In summary, our results suggest that the METTL9/SLC39A7 axis may be a promising diagnostic and therapeutic target for osteoporosis." (PMID 40414869, 2025). "Further investigation of the SLC39A7 expression levels in MSCs revealed that, compared with the control group, the osteoporosis group had significantly elevated SLC39A7 mRNA and protein levels, which was consistent with the findings in bone tissue sections." (PMID 40414869, 2025). "We found that SLC39A7 expression was significantly upregulated in the OVX-treated osteoporosis animal models." (PMID 40414869, 2025). "Furthermore, we confirmed that SLC39A7 expression was significantly upregulated in osteoporosis, which was confirmed at the gene, protein, and tissue levels." (PMID 40414869, 2025).
rheumatic diseases (1 paper, 2026). "The SLC39A7 gene was identified as a candidate gene associated with rheumatic diseases in related GWAS studies, but it is unclear whether it is involved in the genetic process of RA." (PMID 41554047, 2026).